IGF1 (insulin like growth factor 1)
Diseases named in the same sentence as IGF1 in open-access papers (continued):
Sharing a sentence is not in itself a finding about the gene and the disease.
cancer (continued). "Utilization of these two mouse lines allows for a differential evaluation of the effects of elevated GH versus IGF-1 on cancers in vivo." (PMID 33291663, 2020). "The differential effects of fasting on normal (protection) and cancer (sensitization) cells can be mediated, at least in part, by its effects on the insulin-like growth factor 1 (IGF-1) signaling pathway and on glucose levels." (PMID 32393788, 2020). "Researchers found that IGF‐1 also have various biologic effects in cancer development including modulating stem cells, genomic stability, cellular metabolism and angiogenesis." (PMID 32548873, 2020). "Affected individuals present with proportionate dwarfism and other characteristic physical defects, but at the same time are conferred protection against cancer due to low serum levels of IGF-1." (PMID 32296486, 2020). "Research on mice has shown that IGF-1 provides radiation protection, and the use of IGF-1 inhibitors enhances the sensitivity of cancer cells to radiotherapy." (PMID 32190171, 2020). "The insulin-like growth factor-1 (IGF1) pathway is associated with growth, metastasis and clinical outcome of various cancers." (PMID 32733809, 2020). "For instance, many cancers show an increased activation of insulin-like growth factor-1 (IGF-1) signaling pathways and PRDM2a/RIZ1 is able to counteract the IGF-1 receptor and the downstream signaling cascade components ERK1/2 and AKT." (PMID 32290321, 2020). "In this study, we established that IGF-1 mediates a conserved signal through Nrf2 for the induction of BNIP3 expression in cancer cells and MEFs." (PMID 31936236, 2020). "The principal binding protein of IGF-1, IGFBP-3, can reduce IGF-1 bioactivity further inhibiting cancer growth." (PMID 32056047, 2020). "Anamorelin is a ghrelin receptor agonist that can be administered orally and thought to improve cancer cachexia by improving appetite and increasing serum insulin-like growth factor-1." (PMID 33382205, 2020). "IGF-1 signalling is essential for growth and promotes tumourigenesis, cancer cell survival and proliferation, as well as having a highly conserved and potent effect on mitochondrial function and homeostasis." (PMID 31936236, 2020). "A possible explanation is that the IGF1 pathway plays an important role in cancer control, and this cancer-related signal of constraint dominates any adaptive signal related to lifespan." (PMID 32043462, 2020). "Epidemiological studies have shown a relationship between high circulating IGF1 levels and cancer incidence." (PMID 33260481, 2020). "Future mechanistic analyses of newly identified IGF1 target genes will help unravel the connection between the IGF1 pathway, cell metabolism, and cancer protection." (PMID 33182502, 2020). "The role of IGF-1 signaling in cancer and Alzheimer’s disease (AD) will be the focus of the remainder of this treatise." (PMID 32226608, 2020). "The signaling in several types of cancer cells is sustained by adipokines secreted by adipocytes, mainly including leptin, adiponectin, oestrogens, insulin-like growth factor 1 (IGF-1) and hepatocyte growth factor (HGF)." (PMID 32854444, 2020). "Similar to CR animals, dwarf mice are protected from spontaneous and chemically induced cancer, age-dependent declines in immune function, collagen cross-linking, decreased levels of insulin and IGF-1, and increased insulin sensitivity." (PMID 32708786, 2020). "All of these results demonstrated that Wnt/β‐catenin and IGF1 signalling have the ability to inhibit proliferation and induce apoptosis in cancer cells." (PMID 32798252, 2020). "In human cancers, the expression of numerous IGF1 mRNA isoforms (Ea, Eb, Ec, class I and II transcripts, pro-peptides, peptides) was studied, both in in vivo tumor tissues and in a variety of animal models or cultured human/animal transformed cells." (PMID 32977489, 2020).
cancer (continued). "In the tumor microenvironment, IGF-1 drives migration, invasion and proliferation, promotes angiogenesis and maintains cancer stemness." (PMID 32899449, 2020). "The IGF-1/Akt signaling pathway is often impaired in cancer leading to its progression and metastases." (PMID 32211051, 2020). "Since IGF-1 promotes cell proliferation and inhibits apoptosis, its reduction plays a key role in the protection against cancer in mammals." (PMID 33059765, 2020). "IGF-1 is another potent growth factor, which has autocrine, paracrine and endocrine effects and is an important drug target in cancer." (PMID 33291663, 2020). "The analyses revealed that none of the 230 LS patients (up to the age of 85) had developed a malignancy, despite the fact that 66 of them had been treated with IGF1 and two had received hGH as well." (PMID 33182502, 2020). "In a similar fashion, the insulin-like growth factor 1 (IGF1) gene exerts anabolic effects via suppression of apoptosis, and high expression levels of this gene play an important role in cancer." (PMID 33112566, 2020). "Protein restriction prior to surgery exhibited physiological stress protection in mice, whereas low-protein diets in humans under 65 years of age resulted in an overall reduction in IGF-1 levels, cancer, and mortality." (PMID 33287232, 2020). "Two hepatokines known to play a role in skeletal muscle homeostasis and pathogenesis of multiple diseases, including cancer cachexia, are the anabolic factor IGF1 and the catabolic factor IL6." (PMID 31915140, 2020). "Studies of tissue expression indicate distinct roles of IGF1 isoforms in human cancer depending on the type of malignancy and different status of hormone receptors (e.g., estrogen, progesterone, glucocorticoid, androgen) on cancer cells." (PMID 32977489, 2020). "Another limitation is that we had insufficient power to assess potential non‐linear relationships between IGF‐1 levels and cancer." (PMID 32717139, 2020). "In this type of cancer, the hEb peptide shows a pro-proliferative activity, while its nucleolar/nuclear localization points to a more complex role of this IGF1 isoform in CC carcinogenesis." (PMID 32977489, 2020). "Binding of insulin or IGF-1 to their receptors activates many signaling pathways, which can promote the proliferation, invasion, and metastasis of cancer cells, inhibit apoptosis, and lead to the development and progression of many types of cancer cell." (PMID 31942181, 2020). "Independent of the LKB1−AMP−activity, the insulin sensitizer and anti−aging/cancer agent, metformin also inhibits IGF-1 secretion." (PMID 33312162, 2020). "It is noteworthy that NRF2 silencing strongly altered the mitochondrial morphology, biogenesis and turnover, indicating that NRF2 is a key effector of the IGF-1 pathway connecting cell growth to mitochondrial homeostasis and cell survival in cancer." (PMID 32443774, 2020). "This is significant since many of the cancer prevention effects of CR are thought to involve repression of the pro-proliferation anti-apoptotic IGF-1/AKT/mTOR signaling axis." (PMID 32211051, 2020). "Once again, these studies illustrate the complexity of the GH/IGF-1 axis for metabolism, in homeostasis, as well in aging and cancer." (PMID 33312162, 2020). "The IGF-1 signalling pathway is essential for cell growth and survival, and has the potential to enhance tumourigenesis and cancer progression." (PMID 31936236, 2020). "Of note, IGF-1 increases the proliferation of many cancer cells, IL-10, and TGF-β1 inhibits the immune responsiveness of T cells, and VEGFA enhances angiogenesis." (PMID 32908942, 2020). "Multiple members of each of the miRNA family directly target and repress the IGF-1/IGF-1R signaling axis, which is associated with decreased cancer progression and metastases." (PMID 32211051, 2020). "Substantial evidence implicates IGF1 signaling in the initiation and development of a number of cancers including breast cancer." (PMID 32444795, 2020).
cancer (continued). "Transcriptome profiling revealed that E2 (33.3 μg/infusion) lead to down-regulation of insulin growth factor 1 (IGF1), a cytokine that has been suggested to promote cancer survival and tumor metastasis." (PMID 32019139, 2020). "At high concentrations, NDGA disrupts the activation of ERK and AKT signaling pathways activated by IGF-I (insulin-like growth factor-1) and induces apoptosis, the effect being highly important for cancer treatment but also for unwanted side-effects." (PMID 32184727, 2020). "Through receiving the acetylated IGF-1 signaling, IGF-1R is activated to regulate cancer-associated functions, such as the proliferation to promote cancer cell proliferation." (PMID 31217907, 2019). "IGF-1 is involved in promoting the mitogenic, metastatic, and antiapoptotic features of many cancer cells, contributing to the maintenance of cancer cells and progression of cancer." (PMID 30791957, 2019). "ZNF143 was shown to be a determinant of cancer cell motility, as it represses ZEB1, which results in upregulation of E-cadherin to maintain epithelial characteristics of proliferating cancer cells in response to IGF-1." (PMID 30885238, 2019). "IGF-1 pathways are activated by a high concentration of insulin, which then goes on to promote cancer development via the insulin/IGF-1 hybrid receptors." (PMID 31360518, 2019). "Another AKT agonist, IGF-1, also enhanced cancer stem-like traits and reversed the nalbuphine-decreased stem-like phenotype." (PMID 31092275, 2019). "Since the insulin-like growth factor receptor (IGF-1R) is overexpressed in different cancer cells and the IGF-1-dependent pathway plays a major role in cancer cell proliferation, novel approaches aim to inhibit IGF-1R in cancer treatment." (PMID 31284426, 2019). "In order to determine the possible effect of IGF‐1 on cancer cell growth, UM cells were first treated with IGF‐1 at different concentrations (3‐300 ng/mL), and the MTT assay was carried out to detect the cell growth." (PMID 31508890, 2019). "The results indicated that IGF-1 attenuated the anti-cancer efficiency of zoledronic acid on HeLa cells derived CSCs, strongly suggesting that the effects of zoledronic acid on cervical CSCs are mediated, at least in part, by the Erk1/2 and PI3K/Akt pathways." (PMID 30791957, 2019). "Inhibition of IGF-1 reduces cancer growth and metastasis in some cancers such as pancreatic tumors; however, the role of insulin receptor downregulation in the inhibition of cancer progression has not been fully addressed." (PMID 30987250, 2019). "The insulin-like growth factor 1 (IGF-1) system was reported as a key regulator of the cancer growth pathway and it seems that the reduction of insulin levels through diet or medication (e.g. metformin) was beneficial in cancer patients." (PMID 31447604, 2019). "Our results are in line with previous studies in mammals showing that the function of mitochondria is compromised in GHRKO osteocytes and inhibition of IGF1 signaling leads to mitochondrial dysfunction in cancer cells." (PMID 30935132, 2019). "IGF-binding protein-3 (IGFBP-3) is the major carrier protein for IGF-1 and plays a role in cancer, apoptosis, and pathogenesis of ischemia reperfusion after liver injury." (PMID 31057604, 2019). "In fact, IGF-1 and IGFBP-3 levels, as well as the IGF-1/IGFBP-3 ratio, are reported to be associated with cancer risk and tumor development." (PMID 30621039, 2019). "Insulin and insulin-like growth factor-1 (IGF1) are regarded as important players in cancer biology." (PMID 31771180, 2019). "Increased tissue availability of circulating insulin/IGF1 and upregulation of insulin/IGF receptor signaling pathways has been implicated in the formation of different cancers in observational studies." (PMID 31139216, 2019). "Insulin-like growth factor 1 (IGF-1) is a basic peptide composed of 70 amino acids, which is thought to play a central role in metabolism, cancer development, CV diseases and aging." (PMID 31417661, 2019).
cancer (continued). "IGF1 stimulates cell proliferation, decreases apoptosis, and is thus involved in cancer development." (PMID 30654740, 2019). "Recently, it has been recognized that tumor stromal cells support cancer cells’ chemo-resistance by secreting IGF1 and 2 therefore, finding therapeutic targets on tumor stroma has become an urgent task." (PMID 30185144, 2018). "This activation does not only provide survival signals for the fibroblasts, but also activates IGF-1R on cancer cells via IGF-1 that is secreted by fibroblasts and by pancreatic stellate cells (PaSCs) in response to Shh." (PMID 29475434, 2018). "Another important approach in cancer therapy is to inhibit molecular pathways that are crucial for tumor growth and maintenance, such as the insulin-like growth factor-1 (IGF1) pathway." (PMID 29922232, 2018). "The PI3K/AKT signaling pathway, a critical pathway downstream of IGF-1, is responsible for enhancing the proliferation of different kinds of stem cells, as well as increasing the migration of some cancer cells." (PMID 29467020, 2018). "As far as we know, this is the first work that shows the anti-proliferative effect of TSN in cancer cells treated with IGF-1." (PMID 30213025, 2018). "We next examined the effect of endogenous PON2 inhibition on IGF-1 expression in human cancer cell lines including ovary (SKOV3), cervical (HeLa), and lung (A549)." (PMID 29531225, 2018). "IGF1-treated DLD-1 cancer cells were subcutaneously transplanted into NOD/SCID mice, and the tumor-bearing mice were then divided into four groups: sham control, DB (5 mg/kg, 5 times/week), 5-FU (25 mg/kg, 2 times/week), and the combination of DB and 5-FU." (PMID 30257507, 2018). "It is true that overexpression of IGF-1 in cancer or stroma cells promotes cell cycle progression and anti-apoptosis." (PMID 30333226, 2018). "Our data revealed that the three dietary formulation significantly reduced the expression of IGF-1; a tyrosine kinase known to be mitogenic, and playing a crucial role in cancer development." (PMID 29323210, 2018). "Experimental evidence obtained in the last two decades suggests that IGF-1 is able to induce EMT in cancer." (PMID 30111747, 2018). "Overall, these findings strongly indicate that the fasting-mediated sensitization of cancer cells to chemotherapeutic drugs is conferred by the decrease of IGF-1 levels." (PMID 29868472, 2018). "IGF-1 and IGF-1R are known to be abundantly expressed in the PDAC tissue, and activated Insulin/IGF signaling in PDAC cells was found to regulate the basal growth rate of the cancer cells." (PMID 29475434, 2018). "In this meta-analysis, we systematically searched for literature on IGF1 SNPs and cancer in three important databases (PubMed, Embase, and Web of Science)." (PMID 30111277, 2018). "Extremely high IGF1 levels can also explain the development of cancer in children, who suffer mainly from cancers of the brain and white blood cells (Hodgkin’s lymphoma, leukemia)." (PMID 29951370, 2018). "The mechanism of trastuzumab resistance on cancer has been reported in various ways, including the overexpression of insulin-like growth factor I (IGF-1), overexpression of glycoprotein MUC4, and constitutive P13K/Akt activity." (PMID 30960886, 2018). "Accordingly, by secreting CXCL12 and IGF-1, mesenchymal stromal cells from triple negative breast tumors have recently been shown to positively select cancer clones with high Src activity and propensity for bone metastasis." (PMID 29503225, 2018). "A study of the role of insulin and IGF-1 in energy balance and cancer showed that the expression of genes related to the IGF pathway is modified by the absence of physical activity." (PMID 29484135, 2018). "Hyperinsulinaemia promotes cancer cell proliferation by stimulating the insulin receptor directly and insulin-like growth factor-1 indirectly." (PMID 30027404, 2018).
cancer (continued). "Tailored, targeted therapies against stromal insulin/IGF-1 signaling can have beneficial effects both on cancer progression and the deregulated endocrine function." (PMID 29475434, 2018). "The potential role of IGF-1/IGF-1R signaling in cancer progression has been investigated also in lung cancer (LC)." (PMID 30111747, 2018). "IGF-1 has been involved in tumor development and progression because cancer cells have an increased expression of IGF-1 receptors." (PMID 29721213, 2018). "Insulin-like growth factor 1 (IGF1) is a growth and differentiation factor and has been confirmed in various types of cancer cells, including lung cancer cells." (PMID 29559623, 2018). "IGF-1 is a growth factor which can stimulate the proliferation of cancer cells dramatically, and IGF-1R is highly expressed in PC12 cells." (PMID 30213025, 2018). "This inhibitory action of GHRH antagonists on IGF-1 levels in serum has been demonstrated by our group in nude mice bearing various human cancers." (PMID 29983893, 2018). "Next, we measured by ELISA the secretion of IGF-1 in the supernatant of CAFs alone or co-cultured with cancer cells." (PMID 29535813, 2018). "Accordingly, further study would be required to clearly understand the mechanism of action of G-F1 on NK cells and potential involvement of IGF-1 in human cancers." (PMID 30546365, 2018). "The aim of the present study was to determine if an intramuscular injection of PRGF increases circulating levels of the potentially ergogenic growth factor IGF-1 and thus induces skeletal muscle hypertrophy and, in the last instance, cancer." (PMID 30208586, 2018). "Aberrant IGF‐1 signaling has been detected in various human cancer types, and there is evidence implicating IGF‐1 receptor activity in cancer cell proliferation, migration, and invasion as well as in resistance to therapeutic agents." (PMID 29907597, 2018). "Several studies report that the enhanced activation of the IGF-1/IGF-1R signaling axis promotes cancer proliferation and survival." (PMID 30111747, 2018). "The studies have reported that adinopectin (Adipoq), leptin (Lep), ghrelin (Ghr), and insulin-like growth factor (Igf1) hormones have an important role in the cancer development and immunity." (PMID 29511668, 2018). "Evidence from cancers other than PDAC suggest that usage of neutralizing agents against IGF-1/IGF-2 can be a promising approach." (PMID 29475434, 2018). "The cross-talk between CAFs and cancer cells enhances IGF1 secretion by CAFs and PAI-1 (Serpine1) activity in cancer cells." (PMID 29983921, 2018). "Accordingly, blocking the IGF1 signaling pathway, apart from its effect on cancer cells, provides a new target to generate potent antitumor immunity by rescuing the impaired function of DCs." (PMID 29922232, 2018). "Hopefully, future studies will reveal the existence of other tumor-specific routes converging to the EMT, thus enabling our understanding of the invasive and migratory potential of cancer cells in IGF-1-mediated processes." (PMID 30111747, 2018). "IGF-1 has been shown to stimulate cancer cell proliferation, inhibit apoptosis and facilitate metastasis by promoting cell migration and invasion." (PMID 29983893, 2018). "Using the cancer genome atlas database we also found that increased gene expression of Igf-1, Igf-2, and the M2-like macrophage markers cd163 and mrc1 positively correlates with reduced survival in breast cancer patients." (PMID 29367764, 2018). "Higher IGF1 levels are a prerequisite for greater physical growth, which explains why cancer mortality increases with increasing adult stature." (PMID 29951370, 2018). "IGF-1 induces the EMT in most cancer cells, whereas IGF-1R activation leads to downregulation of E-cadherin and upregulation of N-cadherin, vimentin, and fibronectin." (PMID 30111747, 2018). "Various experimental and clinical studies have demonstrated the role of IGF-1 in growth and metastasis of many cancers." (PMID 29983893, 2018).